MYD88 (MYD88 innate immune signal transduction adaptor)
Diseases named in the same sentence as MYD88 in open-access papers (continued):
Sharing a sentence is not in itself a finding about the gene and the disease.
infection (continued). "Moreover, MEFs isolated from wild-type, TLR-9−/−, TLR-3−/−, MAVS−/− and MyD88−/− and TRIF−/− C57BL/6 mice embryos were all producing similar levels of IFN-β upon MVMp infection, indicating that neither TLRs nor RLRs are involved in the IFN response triggered by replicating MVMp in MEFs." (PMID 37111493, 2023). "The results showed that siRNAs targeting RIG-I, MDA5, and TRIF but not MAVS or MyD88 significantly reduced the mRNA of IFN-β, demonstrating that RIG-I/MDA5-mediated RLRs signaling pathway and TRIF-mediated TLRs signaling pathway involved in the production of IFN-β during FJzz1 infection." (PMID 35958569, 2022). "Host inflammatory activation through Myd88 is required for killing of a CEA10-derived strain but not sufficient for killing of an Af293-derived strain, further demonstrating the role of fungal-intrinsic differences in the ability of a host to clear an infection." (PMID 30071103, 2018). "In this study, lack of MyD88 decreased the frequency of activated CD8+ T cells and increased the number of CD4+ T cells, which could also account for the attenuated liver immunopathology at late stages of infection." (PMID 29049365, 2017). "Although we have not studied the memory response in the infection model here, we also found a significant lower percentage of cells expressing high levels of the CD44 activation/memory marker among CD4+ T cells lacking IL-1R expression, as well as among Myd88−/− and Il18r1−/−CD4+ T cells." (PMID 28895840, 2017). "However, with the inhibition of siNF-kB 1, a dramatic up-regulation of MyD88 at 1 h post-infection was observed, while no significant change was found for TRAF6, except for an even lower expression at 4 h post-infection for some unknown reason." (PMID 21637513, 2009).
tumor (499 papers, 2009 to 2026). "MyD88 expression demonstrated a significant association with tumor budding grade (p=0.022), showing progressive increases from low-grade (53.8%) through intermediate-grade (70.6%) to high-grade tumors (83.3%)." (PMID 40703545, 2025). "The TLT subtype featured upregulation of genes involved in B-cell receptor signaling, cell cycle, DNA damage and repair, higher frequencies of CNVs and MYD88 mutations, elder ages, larger tumor sizes, and significantly poorer survival." (PMID 39866884, 2025). "The MYD88 mutation was detected in the 4 patients by next generation sequencing of tumor tissue genes." (PMID 41256314, 2025). "The MyD88 rs138284536 variant demonstrated even stronger disease association (OR=20.01, 95% CI: 4.72-84.83) and revealed complex interactions with tumor biology." (PMID 40703545, 2025). "Third, we established strong associations between TLR4/MyD88 pathway activation and aggressive tumor features, including perineural invasion, high-grade tumor budding, and lymph node metastasis." (PMID 40703545, 2025). "The pathogenesis of THRLBCL involves several genetic alterations also seen in DLBCL, including overexpression of BCL2 and mutations in TNFAIP3 and MYD88 (L265P), which promote tumor cell survival." (PMID 41141099, 2025). "MYD88 (73%) was the most common mutation in primary tumor tissues, followed by the mutation of PIM1(64%) and CD79B (55%)." (PMID 40475774, 2025). "Distinctly, central genes including MYD88 are implicated in apoptosis and immune regulation, reinforcing the critical role of this miRNA in modulating tumor biology." (PMID 40869426, 2025). "This is supported by experimental models showing that MyD88-dependent signaling influences tumor-associated inflammation and progression." (PMID 40703545, 2025). "TLR4 is known to promote metastasis in various cancers by influencing the EMT process, and its interaction with MyD88 is linked to increased tumor development and progression in intestinal tumorigenesis." (PMID 39390599, 2024). "Elevated MyD88 expression is closely associated with aggressive tumor characteristics, suggesting its potential as a valuable prognostic marker and therapeutic target." (PMID 38347830, 2024). "Recently, long noncoding RNAs (lncRNAs) showed great potential as tumor diagnostic biomarkers, and lnc-MyD88 was previously identified as a carcinogen in HCC." (PMID 36793272, 2023). "Multiple cell types within the tumor microenvironment express MyD88 and its associated upstream receptors." (PMID 37244938, 2023). "Genomic characterization of WM tumor cells has identified recurrent somatic mutations in MYD88 (>95% patients) and CXCR4 (>30% patients) genes, and deletions involving chromosome 6q (del6q; ∼50% patients), among other alterations." (PMID 37493341, 2023). "To determine how cell type-specific loss of Myd88 expression affects tumor growth and responses to radiation therapy (RT), we used two pancreatic cell lines Panc02-SIY and the more aggressive PK5L1940." (PMID 37244938, 2023). "MYD88 mutation defined the main tumor clone in these patients (it was present in 91.5% and 26.5% of cells, respectively)." (PMID 37493341, 2023). "Here, we focus on the underlying molecular mechanisms of the MyD88 inhibitor targeting MDSCs and provide novel insights into therapeutic strategies targeting MDSCs in tumor-bearing hosts and cancer patients." (PMID 35089465, 2022). "Myd88 plays an important role in the tumor growth in DLBCL, which is molecular diagnostic target for VRL." (PMID 35268483, 2022). "LPS-mediated induction of cytokine transcription in PC3 cells was TLR4- and Myd88-dependent, suggesting that pathogen-associated molecular pattern recognition mechanisms are comparable between tumor and immune cells." (PMID 36539532, 2022). "Recently, another synthesized ODN-based TLR7/9 antagonist HJ901 was shown to significantly inhibit tumor cell proliferation and tumor growth in cell lines or animal models carrying the MyD88 L265P mutation." (PMID 36479129, 2022).
tumor (continued). "The high-risk group was characterized by higher expression of CD163, which is a marker of M2-like tumor-associated macrophages (TAMs), and MYD88, which is a marker of NF-kappa-B activation, cytokine secretion, and inflammatory response." (PMID 34945004, 2021). "In this context, MYD88 has also been shown to play an integral role in spontaneous tumour development in mice with a mutation in the adenomatous polyposis coli (APC) gene and in carcinogen-induced colon tumour development." (PMID 33597599, 2021). "The earliest studies evaluating the utility of ctDNA focussed on the MYD88 L265P mutation due to its presence in greater than 80% of PCNSL tumours." (PMID 35844685, 2021). "Activation of TLR4 signaling occurs in both MyD88-dependent and MyD88-independent pathways and associates with regulation of tumor progression and immune evasion via production of cytokines, chemokines, and type I IFNs." (PMID 34715891, 2021). "We have previously employed the same methods in PCNSL and achieved a high detection rate of MYD88 L265P and a 100% match of the MYD88 mutation status between CSF and tumor." (PMID 33918936, 2021). "detected cfDNA evaluated by droplet digital PCR in 14 patients, among whom the MYD88 L265P mutation was identified in tumor-derived DNA." (PMID 33816315, 2021). "In this context, MYD88, a downstream signalling molecule of Toll-like receptors that initiates inflammatory signalling cascades, has a critical role in tumour development in mice and its gene mutation was found in human cancers." (PMID 33597599, 2021). "Formalin-fixed paraffin-embedded tumor samples underwent polymerase chain reaction assay to detect MYD88 mutation." (PMID 34377990, 2021). "Tumor cells with LATS1/2 deficiency secreted nucleic acid-rich EVs to facilitate TLRs-Myd88/TRIF signaling and type I IFN production, which accelerated DC maturation, CD8+ T lymphocyte expansion, and tumor growth arrest." (PMID 32849504, 2020). "This pooled analysis demonstrated that the MYD88 L265P mutation significantly correlated with the immune-privileged (IP) tumor site." (PMID 33050534, 2020). "Activation of TLRs usually induces recruitment of the adapter molecule myeloid differentiation primary response protein 88 (MyD88), and activation of TLR/MyD88 typically leads to the activation of NF-κB, which has been linked to the progression of tumours." (PMID 32760436, 2020). "The activation of NF-κB, which is commonly induced by TLR2/MyD88, has been linked to the progression of tumours." (PMID 32760436, 2020). "A second somatic, highly recurrent genetic event in WM consists of activating C-terminal mutations in the CXCR4 gene, which appear to enhance tumor cell dissemination and survival and mostly occur in the context of a mutated Myd88 allele." (PMID 33343574, 2020). "Previous study suggested that abnormal expression of MyD88 was closely associated with the development of tumor and resistance of drugs." (PMID 32477927, 2020). "MYD88 L256P was the most common mutation detected in both CSF and primary tumor samples, followed by mutations of PIM122 and B2M23 genes." (PMID 33068336, 2020). "The myeloid differentiation primary response 88 (MYD88) mutation is highly prevalent in approximately 90% of patients with WM, which triggers the growth of tumor cells through BTK involved in the NF-κB pathway." (PMID 33005100, 2020). "TLR4 signaling of H22 hepatoma cells was transduced through myeloid differentiation primary response 88 (MyD88) to the actin cytoskeleton, which caused the release of miR let-7b containing membrane-derived vesicles by the tumor cells." (PMID 31766495, 2019). "A recurring somatic mutation in MYD88 (MYD88 L265P) was identified in 91% of WM patients by paired tumor/normal whole genome sequencing.2▪ By more sensitive allele-specific PCR testing, MYD88 L265P was expressed in 93% to 97% of WM patients." (PMID 35309816, 2019).
tumor (continued). "The presence of L252P causes stimulus-independent activation of MyD88-directed signals and constitutive activation of NFκB, conferring a pro-survival phenotype in these tumours." (PMID 30786893, 2019). "Higher tumor burden was demonstrated in APC(Min/+) mice following inoculation of clinical isolates of F. nucleatum, and was associated with activation of TLR4/MyD88/NFκB signaling and recruitment of tumor-infiltrating myeloid cells." (PMID 30413188, 2018). "L252P mutation in MyD88 was identified in tumour samples from 49 of 54 patients with the incurable form of the disease." (PMID 30583727, 2018). "Treatment of MyD88-deficient mice carrying B16.F1 tumors with attenuated Salmonella was ineffective in regressing tumor growth, indicating that bacterial therapy of tumors is dependent on TLR-MyD88 signaling." (PMID 29765907, 2018). "As approximately 40% of ABC DLCBL biopsies harbor MyD88 mutations, MyD88 represents the most frequently mutated oncogene in this tumor entity." (PMID 29587428, 2018). "Several studies using genetic or chemical carcinogenesis models involving Myd88 deficient mice have shown MyD88 to either promote or suppress tumor development." (PMID 28201999, 2017). "High level copy loss was observed in cases 101, 102, and 104, while case 103 also harbored a high level loss given the presumed tumor content of 30% (based on MYD88 L265P at 0.15 variant allele frequency)." (PMID 28002793, 2017). "We found that the incidence of MYD88 L265P mutation in DLBCL patients varies from tumor site to tumor site." (PMID 28496180, 2017). "This pooled analysis showed that the tumor location of origin in DLBCL contributes to the prevalence difference of MYD88 L265P mutation." (PMID 28496180, 2017). "Myeloid-derived suppressor cells and tumor-associated macrophages express TLR2 that activates MyD88 signaling to promote invasion and metastasis." (PMID 29041928, 2017). "Although TLR/MyD88 activity is associated with tumour promotion and Nod activation with tumour prevention, our study shows that depending on the nature and cellular location of the specific commensal, the roles can be reversed." (PMID 28300841, 2017). "In this meta-analysis, the MYD88 L265P mutation in DLBCL showed a significant difference according to tumor sites." (PMID 28496180, 2017). "MyD88 evokes inflammatory signal that causes nuclear translocation of NF-κB and regulates apoptosis in tumor cells." (PMID 29041928, 2017). "Statistical analysis showed that a higher expression level of Lnc-Myd88 in HCC was associated with increased tumor size, worse tumor differentiation grade and metastasis." (PMID 29022910, 2017). "This pooled analysis demonstrates that the MYD88 L265P mutation is significantly associated with the tumor sites and molecular subtypes in DLBCL patients." (PMID 28496180, 2017). "VAFs of this mutation in relation to MYD88 indicated that it was present in half of the tumor clone in two patients and in the whole clone in the other patient, staying the same at both moments." (PMID 28841204, 2017). "The Toll-Like Receptor (TLR) signaling adapter molecule MYD88 is the most frequently mutated gene in these neoplasms." (PMID 27303665, 2016). "Here, we describe enhanced anti-tumor efficacy of an in vivo electroporation-delivered DNA vaccine by inclusion of a genetically encoded chimeric MyD88/CD40 (MC) adjuvant, which integrates both innate and adaptive immune signaling pathways." (PMID 27741278, 2016). "39% of tumor samples contain mutations in MYD88, and strikingly, 29% of those mutations result in a single nucleotide change from leucine into proline at position 265 (L265P)." (PMID 25132836, 2014). "The co-expression of TLR4/MyD88 or TLR4/MyD88/NF-κB was significantly associated with tumor stage and histologic type." (PMID 22985132, 2012). "MYD88 rs7744 was significantly associated with tumor size and lymph node involvement." (PMID 42278290, 2026).
tumor (continued). "Furthermore, aberrant MyD88 signaling is implicated in the proliferation and metastasis of tumor cells, processes that are significantly correlated with an adverse patient prognosis." (PMID 39744584, 2025). "And, a hallmark of WM is MYD88 L265P mutation, which may facilitate the localization of tumor cells to extranodal sites in transformed WM." (PMID 41269394, 2025). "The association between MyD88 expression and tumor budding grade demonstrates biological plausibility, as MyD88-dependent signaling promotes epithelial-mesenchymal transition programs crucial for tumor invasion." (PMID 40703545, 2025). "Their findings revealed that MyD88 promotes the recruitment and activation of various immune cells, including M1-like tumour-associated macrophages, neutrophils, dendritic cells, CD4+ and CD8+ T cells, NK cells, and NKT cells, within the tumour microenvironment." (PMID 40005571, 2025). "Supporting these observations, previous studies have shown that CCRL2 can modulate innate immune signaling via direct interactions with receptors such as TLR4, enhancing its plasma membrane stability and promoting MyD88-dependent NF-κB signaling in tumor-associated macrophages." (PMID 40867595, 2025). "MYD88 gene mutations were found to cause activation of the NF-κB pathway, which was implicated in the upregulation of pro-inflammatory cytokines as well as genes involved in the survival and proliferation of tumor cells." (PMID 39169396, 2024). "Additionally, as BTK inhibition has been previously shown to synergize with IRAK inhibition, JH-X-119-01 was co-treated with the BTK inhibitor ibrutinib, which showed synergistic tumor cell-killing effects in MYD88-mutated B-cell lymphoma cells." (PMID 38792088, 2024). "In our cohort, only one adult tumor showed both MYD88 and CD79B mutations." (PMID 38730692, 2024). "Moreover, the known effects relate to the comparison of healthy B-cells with MYD88(L265P) carriers, whereas our analysis compares tumour cells with multiple additional mutations against each other, which can introduce confounding effects." (PMID 39501370, 2024). "Additionally, the MyD88/NF-κB signaling pathway governs the expression of various cytokines, notably IL-6 and IL-8, which are intricately linked to tumor progression and the survival of BCSCs." (PMID 38347830, 2024). "In addition, the MyD88/IL1 receptor (IL1R) axis upregulates programmed cell death (PD)-1 expression on tumor-associated macrophages (TAMs) via promoting recruitment of NF-κB to the Pdcd1 promoter, which sustains their immunosuppressive function in melanoma." (PMID 35309296, 2022). "Nevertheless, the inflammatory pathways are also affected by immune checkpoint inhibitors, nivolumab and ipilimumab, that caused changes in NLRP3 inflammasome, MyD88 complex NF-κB/p65 expression, and in several interleukins in co-cultures of lymphocytes with tumor or with cardiac cells." (PMID 34073506, 2021). "Tumor-specific M13 filamentous bacteriophages, developed to target tumor microenvironment, can activate macrophages and tumor-associated macrophages, inducing secretion of pro-inflammatory mediators via MyD88." (PMID 34711839, 2021). "Tumor necrosis factor receptor (TNFR) signaling was found to be a negative regulator of M2 polarization in tumor-associated macrophages (TAMs), and myeloid differentiation primary response 88 (MyD88) was shown to suppress M2 gene expression in TAMs, leading to an M1 phenotype." (PMID 34209703, 2021). "Studies on the administration of M13 and T4 phages to mice tumor models have demonstrated that the mechanism by which anti-tumor phages induce tumor elimination is mediated by the activation of tumor-associated macrophages in a Myeloid differentiation primary response 88 (MyD88)-dependent way." (PMID 32899720, 2020).